IL6 (interleukin 6)
Diseases named in the same sentence as IL6 in open-access papers (continued):
Sharing a sentence is not in itself a finding about the gene and the disease.
COVID-19 (continued). "Immunomodulatory therapies (IMT) (e.g., corticosteroids, IL‐6 inhibitors, GM‐CSF inhibitors, methotrexate, calcineurin inhibitors, and antitumor necrosis factor agents) have been used to treat the hyperinflammatory response seen in severe or critical COVID-19." (PMID 39618741, 2024). "Although the mechanism of COVID-19-related deaths is unclear, an overarching hypothesis involves a cytokine storm, induced by enhanced IL-6 signaling." (PMID 39197405, 2024). "Consequently, some clinicians prefer using IL-6 inhibitors, such as tocilizumab, to mitigate lung damage in COVID-19 patients." (PMID 38391578, 2024). "Of note, decreased lymphocyte subsets and increased cytokines (IL-6, IL-8, IL-10 and IFN-γ) may aid the early identification of patients at risk of severe and critical COVID-19 and provide more definitive and timely approaches for treatment." (PMID 38173531, 2024). "In conclusion, higher levels of the biomarkers CRP, IL6, IP10, ferritin, IFNα, IL8, IL1RA, MCP1, and lower levels of RANTES measured within 7 days of symptoms onset were associated with increased risk of hospitalization due to COVID-19 progression." (PMID 39664394, 2024). "In COVID-19, elevated IL-6 levels are correlated with the severity of the cytokine storm." (PMID 39866999, 2024). "IL-6 may act as a target for therapeutics and, a blockade of IL-6 function by Tocilizumab has been described as a treatment of the inflammatory process COVID-19-related." (PMID 38617587, 2024). "In COVID-19 patients, abnormal activation of macrophages expressing M1/M2 polarization markers (CD68, CD80, CD163, and CD206) in the lung is associated with the production of cytokines, including IL-6, IL-10, and TNF-α, as indicated by previous studies." (PMID 39100091, 2024). "IL-6 is a critical cytokine involved in the pathogenesis of CRS in patients with COVID-19." (PMID 39359733, 2024). "Thus, in children with COVID-19 and appendicitis, an increase in pro-inflammatory cytokines IL-1 and IL-6, as well as anti-inflammatory cytokines IL-4 and IL-10, is observed." (PMID 38397914, 2024). "Interleukin 6 (IL-6), a significant cytokine, plays a crucial role in the pathogenesis of COVID-19." (PMID 39337343, 2024). "In COVID-19 patients with cardiovascular disease, fibrinogen and IL6 levels positively correlated." (PMID 38474287, 2024). "Furthermore, recently, Raloxifene and Bazedoxifene were found to be capable of interfering with IL-6 signaling in severe COVID-19 patients, showing positive effects on Acute Respiratory Distress Syndrome." (PMID 39337891, 2024). "Our study suggests that for asymptomatic or mild COVID-19 patients with low IgG levels, using IL-6 blockers, receiving vaccinations, and/or treating comorbidities can enhance the immune response to SARS-CoV-2, thereby reducing the risk of long COVID and improving their quality of life." (PMID 39717543, 2024). "Having found that IL-6 and sIL-6R serum levels are increased in acute severe COVID-19 patients, we sought to investigate whether this is a specific effect or whether similar proteins are also increased in the serum of these patients." (PMID 39835136, 2024). "However, IL-6 has been identified as the master regulator of the cytokine storm associated with severe disease in respiratory syndromes and blocking the IL-6 pathway with immunotherapies have also shown to be an effective treatment against severe COVID-19." (PMID 39541407, 2024). "Our study demonstrated that simple whole-blood morphology analysis and LDH and IL-6 levels may also have additional predictive value for the determination of COVID-19 complications." (PMID 38982355, 2024). "In the present study, nine variables, including age, preterm birth, underlying condition, seizures, NLR, IL-6, LDH, D-dimer, and co-infection were selected as the predictors for RSV-associated SALRTI in post-COVID-19 era, and were further integrated into a prediction nomogram." (PMID 39114651, 2024).
COVID-19 (continued). "Except for IL-8 decreased in the second trimester after infected with SARS-CoV-2, IL-2, TNF-α, TNF-β, IFN-γ, IL-4, IL-5, IL-6, IL-10, IL-17A, IL-17F, IL-22, IL-1β and IL-12p70 didn't change in the three trimesters between healthy pregnancies and pregnant women with COVID-19." (PMID 39113896, 2024). "Also, anti-IL-6 antibody treatment (Tocilizumab) decreases symptomology in conditions such as RA, and COVID-19." (PMID 38840141, 2024). "Data regarding the demography, comorbidities, presenting symptoms, method of diagnosis of COVID-19, computed tomography (CT) severity score, Interleukin 6 (IL-6), D-dimer, oxygen requirement, number of days in hospital and outcome were collected for both groups." (PMID 39398090, 2024). "A recent study indicated that acalabrutinib may be a valuable treatment for COVID-19 by inhibiting monocyte IL-6 production." (PMID 38638439, 2024). "Thus, the present study aimed to investigate the association between the severe form of acute COVID-19 and long COVID with the gene expression of STING and cGAS and the plasma levels of IFN-α, TNF-α and IL-6." (PMID 38424312, 2024). "Interestingly, CRP, IL6 and IP10 had the most robust association with hospitalization and severe COVID-19, with CRP having the highest discriminatory capacity for hospitalization, and IL6 for severe COVID-19." (PMID 39664394, 2024). "Having shown that IL-6 and sIL-6R serum levels are increased in acute severe COVID-19 patients, we sought to determine how much of the IL-6 is trapped in inactive complexes and how much is free and able to do harmful activities, thereby potentially contributing to COVID-19 pathology." (PMID 39835136, 2024). "In an external COVID-19 cohort of 219 patients from Massachusetts General Hospital, a previously identified proteomic eGC signature correlated with IL-6 (rs=-0.58, p < 0.0001) and predicted the combined endpoint of 28-day mortality and/or intubation (ROC-AUC: 0.86 [95% CI: 0.81–0.91], p < 0.001)." (PMID 38598083, 2024). "IL6 levels are significantly elevated in the blood of patients with severe COVID-19." (PMID 38543303, 2024). "This highlights the potential therapeutic implications of targeting IL-6 in managing COVID-19, where mitigating the cytokine storm could improve patient outcomes." (PMID 39203987, 2024). "Moreover, the systemic inflammatory response triggered by COVID-19, characterized by elevated levels of pro-inflammatory cytokines (e.g., IL-6, TNF-a), can exacerbate liver injury through immune-mediated mechanisms and microvascular thrombosis." (PMID 39492990, 2024). "Overall, establishing the complex relationship between high altitude, IL-6, hepcidin, ferritin, C-reactive protein, and zinc in the context of COVID-19 could provide insight into the pathogenesis of the disease." (PMID 39062181, 2024). "Low vitamin D levels are inversely correlated with high IL-6 levels in COVID-19 patients." (PMID 39655234, 2024). "MiR-145-5p also targets SERPINE1, as well as tissue factor and IL6 genes, suggesting that tissue factor activation might have been higher in COVID-19 patients." (PMID 39237986, 2024). "Notably, exposure of ECs to COVID-19 plasma characterized by elevated proinflammatory cytokine levels (specifically, IL-1β, IL-6, and TNF-α) precipitated a redox-sensitive upregulation of SGLT-2 expression." (PMID 38448675, 2024). "Blocking IL-6 signaling as a therapeutic intervention has been extensively studied in many diseases, and COVID-19 randomized controlled clinical trials with biologics targeting the IL-6 receptor, including the Tocilizumab antibody, have shown evidence of clinical benefit." (PMID 38745756, 2024). "Also, increased expression levels of IL-6 and TNFα were found in the lung biopsy of a severely ill patient with COVID-19 who subsequently died." (PMID 39457048, 2024). "Furthermore, an association between elevated IL-6 values and development of AKI was demonstrated in COVID-19 patients who were admitted to the ICU." (PMID 38336628, 2024).
COVID-19 (continued). "Although anecdotal data on IL6 inhibitors (e.g. anti-IL6R antibody Tocilizumab) in pregnant women with inflammatory disorders such as rheumatoid arthritis or severe COVID-19 during pregnancy are reported, systematic studies of safety and efficacy have not been reported thus far." (PMID 38895127, 2024). "In addition, the ACLF+COVID-19 group had higher IL-6 levels (161.43 [82.75 - 479.9)] vs 7.96 [29.3-18.54]; p=0.004), IL-8 levels (302.77 ± 264.24 vs 7.53 ± 9.24; p=0.041), and IL-17 levels (28.89 ± 24.43 vs 0 [0-2.76]; p=0.022) than the COVID-19 group." (PMID 39867341, 2024). "Because HM and recent chemotherapy have been associated with poor outcomes among patients with cancer and COVID-19, the anti-inflammatory effects of nirmatrelvir-ritonavir and azvudine were determined via the expression levels of IL-6, PCT, CRP, and various serological laboratory indicators." (PMID 39059144, 2024). "The higher median IgM, IgA, and IgG1 values in the sera of the MIS-C cohort to some of the COVID-19 Ags may relate to the higher type-2 cytokines (IL-4, IL-5, IL-6, and IL-13) and IL-21 enhanced Tfh activity known to promote B-cell activities." (PMID 38932242, 2024). "The role of serological components in causing cardiovascular damage in COVID-19 is further corroborated by a significant negative correlation of IL-6, TNF-α, IL-1β, IL-10, and CRP levels with cardiomyocyte viability." (PMID 38041432, 2024). "After being confirmed that COVID-19 patients have higher levels of Gal-1, Gal-3, and prostaglandin E2 (PGE2) compared to healthy patients, the positive association between Gal-1 and IL-1β, IL-6, IL-10, IL-23, IL-33 was studied and proven." (PMID 38540252, 2024). "The results showed that COVID-19 patients had significantly higher levels of all three cytokines compared to the control group: IL-6 at 165.85 ng/mL (±20.13) vs. 86.68 ng/mL (±17.30); IL-1β at 52.30 ng/mL (±11.71) vs. 6.30 ng/mL (±6.61); and TNF-α at 179.54 ng/mL (±28.92) vs. 18.50 ng/mL (±4.25)." (PMID 39201618, 2024). "In contrast, individuals without a COVID-19 but who have a moderate to severe risk of OSA displayed higher serum IL-6 levels (median 14, IQR 25.5) than those with a mild risk of OSA (median-8, IQR 5, p < 0.05)." (PMID 38476500, 2024). "Moreover, lactoferrin administration is able to reduce systemic levels of IL-6 in COVID-19 and PACS patients; ferritin and D-dimer serum levels have also been reported to have decreased." (PMID 39200115, 2024). "In conditions of “cytokine” storm, IL-6 can be produced by vascular smooth muscle cells, which may also contribute to the development of local inflammatory response in the COVID-19." (PMID 38921725, 2024). "However, due to the widespread systemic vascular involvement in COVID-19, it appears plausible that anti-IL-6 therapy would have reduced damage to the eGC." (PMID 38598083, 2024). "Nowadays, the role of IL-6 in COVID-19 patients with VTE has drawn more and more attention." (PMID 38493138, 2024). "This systematic review and meta-analysis pointed out that elevated levels of IL-6 and ferritin were significantly possitive associated with VTE, thus could be used as biological predictive indicators of VTE among COVID-19 patients." (PMID 38493138, 2024). "IL-6 and IL-1β are pivotal targets of antirheumatic agents, and there is evidence that blocking the IL-6 receptor can reduce lung involvement and acute cardiovascular complications in patients with COVID-19 by inhibiting the systemic inflammatory response." (PMID 38455049, 2024). "In the present study, we found that the combination of SpO2 and IL-6 at admission may predict critical respiratory illness in patients hospitalized with COVID-19." (PMID 38394183, 2024). "The advancement of COVID-19 is driven by heightened oxidative phosphorylation, inflammatory responses associated with reactive oxygen species, and the displacement of inflammatory responses mediated by TNF and IL-6." (PMID 38337760, 2024).
COVID-19 (continued). "CRP, IL6, and IP10 could support clinical decision making, particularly the need of referral or admission, by identifying high-risk COVID-19 patients in an outpatient setting or emergency service." (PMID 39664394, 2024). "Thus, excessive IL-6 levels in COVID-19 patients correlate with severe disease, including pulmonary inflammation, lung damage, and multiple organ failure." (PMID 38707035, 2024). "In this study, we identified that hospitalization due to COVID-19 was characterized by high levels of IL-6, MIG, IP-10, and IL-1R antagonist in the second week of illness and high levels of IL-6 in the first week of illness in comparison to milder illness in the community." (PMID 39650666, 2024). "IL-6 participates in and is central to the “cytokine storm”, which is related to the development of severe acute respiratory distress syndrome and is a fatal outcome of coronavirus disease 2019 (COVID-19)." (PMID 38248262, 2024). "The results presented in our study are a proof of principle that the expression of IL-1β, IL-6 and IL-8 genes, coding key proteins of the COVID-19 “cytokine storm”, can be inhibited by aged garlic extract (AGE) and the AGE bioactive compound S-allyl-cysteine (SAC)." (PMID 39770027, 2024). "This suggests that COVID-19's hyper-inflammatory state, primarily driven by Th1 cells and IL-6, may promote autoimmunity." (PMID 40735669, 2024). "Independent of initial disease severity, having received dexamethasone during acute COVID-19 was associated with higher levels of IL6, IL10, sCD14 and CRP compared to those who did not receive dexamethasone, in multivariable analyses." (PMID 39008486, 2024). "Moreover, these patients frequently exhibit heightened levels of interleukin 6, which can exacerbate the cytokine storm seen in severe cases of COVID-19." (PMID 38758248, 2024). "Both IL-6 and IL-8 have been broadly considered as prognostic biomarkers in COVID-19." (PMID 39916956, 2024). "In high-income countries (HICs), clinical outcomes for patients with severe COVID-19 have improved substantially over time, in part due to targeted administration of immunomodulatory therapeutics (i.e., corticosteroids, interleukin-6 and JAK1/2 antagonists) and widespread SARS-CoV-2 vaccine uptake." (PMID 38368384, 2024). "Similarly, a study conducted on patients with severe COVID-19 revealed that the levels of IL-2, IL-6, IL-10, and TNF-α were significantly higher compared to non-severe patients." (PMID 38355623, 2024). "As with IL-6, IL-10 has been proposed as a predictive marker, suggesting that measuring IL-6 and IL-10 levels could be useful in assessing the prognosis of patients with COVID-19." (PMID 38601541, 2024). "Furthermore, some chemokines and cytokines as well as induced protein 10 (IP10), MCP-1, IL-6, and IL-1 were considerably enhanced in severe COVID-19, MERS, and SARS, according to recent investigations." (PMID 38694122, 2024). "The release of pro-inflammatory cytokines (such as IL-6) after COVID-19 vaccination may dysregulate the T cell response, which is largely involved in the development of BP." (PMID 39340046, 2024). "In conclusion, incorporating delirium into COVID-19 clinical scores enhances their performance, and although IL-6 remains a valuable predictor, delirium alone may offer a more practical and cost-effective approach." (PMID 37329431, 2023). "The present study showed that the combination of BCc1 and Hep-S nanomedicines along with the standard treatments of COVID-19 reduced IL-6 as an important mediator of CSS and can be studied and evaluated in future clinical phases to present a novel immunomodulator." (PMID 37951972, 2023). "The findings of the study highlighted that plasma levels of TNF, interleukin-6, and interleukin-8 were considerably lower among COVID-19 patients than among septic shock patients with acute respiratory distress syndrome, which elucidates a lower acuteness of disease despite acute lung injury." (PMID 38161941, 2023).
COVID-19 (continued). "However, we found that IFN-γ and IL-6 of COVID-19 patients with diabetes were significantly higher than those of patients without diabetes." (PMID 38095633, 2023). "Thus, it is crucial to measure serum IL-6 concentrations rapidly and repeatedly during treatment courses to facilitate the timely identification of either CAP or COVID-19 patients at risk of developing acute respiratory failure." (PMID 37214473, 2023). "IL-6 has been identified as an important marker of poor COVID-19 evolution." (PMID 37632046, 2023). "Various studies have reported elevation in IL-6 in COVID-19 patients." (PMID 37051070, 2023). "Patients with severe COVID-19 have a high level of circulating IL-2, IL-6, IL-7, IL-10, and IFN-γ." (PMID 37654571, 2023). "In addition, the authors suggested that the measurement of IL-6 and IL-10 concentrations should be an option to predict mortality in COVID-19." (PMID 36766961, 2023). "Importantly, this benefit is additive to corticosteroid treatment, indicating the blockade of IL-6 is a useful treatment approach for patients with severe COVID-19." (PMID 37515150, 2023). "Wilcoxon rank test and Welch’s test showed that IL-6 could play a key role in the onset of quantitative (ageusia and hypogeusia) and qualitative (parageusia) taste disorders in COVID-19 patients." (PMID 35801415, 2023). "In contrast, severe COVID-19 includes sustained expression of these markers with additional signatures including IL-6, IL-10, IL-18, IL-23, TNF, and eotaxin among others suggesting that specific timing and failure to resolve inflammatory responses are important factors in disease progression." (PMID 37491352, 2023). "However, a recent single center study was able to show the predictive capacity of IL-6 for survival among a cohort of severe COVID-19 cases." (PMID 37937220, 2023). "HMGB1, NLRP3 and IL-6 levels were positively correlated with headache in patients with COVID-19." (PMID 37940864, 2023). "A review study observed that variants in cytokine genes such as IL-1β, IL1R1, IL1RN, IL-6, IL-17A, FCGR2A, and TNF may be associated with disease susceptibility and/or severity, cytokine storm, and/or COVID-19 complications like thrombosis." (PMID 37662953, 2023). "The mechanism of the increase in IL-6 in COVID-19 patients may be the release of IL-6 from respiratory epithelial cells, CD14 + CD16 + monocyte-macrophages and lymphocytes after infection." (PMID 37310657, 2023). "Therefore, the role of IL-6 in COVID-19 deserves special attention, even if its contribution to predicting the severe case is not fully understood." (PMID 37834356, 2023). "At the acute infection phase, severe/critical COVID-19 patients had significantly higher IL-6 levels than non-severe patients, suggesting a pathogenic role of IL-6 in a cytokine storm." (PMID 36810114, 2023). "In clinical chemistry, C-reactive protein (CRP), procalcitonin (PCT), interleukin-6 (IL-6), and ferritin are known biomarkers that are elevated in the setting of acute inflammation and may help predict an unfavorable outcome in COVID-19." (PMID 37937220, 2023). "It is known that IL-6 is elevated in patients with severe COVID-19 owing to an excessive immune response, which correlates with disease severity; thus, the usefulness of tocilizumab as a therapeutic agent against COVID-19 has been investigated." (PMID 37352037, 2023). "Moreover, hyperactivation of the PI3K-Akt signaling pathway is involved in viral entry into cells and in the induction of pro-inflammatory mediators (TNF-α, IL-6, etc.)that significantly contribute to the etiology of COVID-19." (PMID 36817449, 2023). "Also, numerous studies have shown that COVID-19 patients have increased levels of IL-1β, IL-2, IL-6, IL-10, TNFα, IFNγ, and that these cytokines correlate with the severity of the disease." (PMID 36835858, 2023). "In summary, CSF IL-6 levels are very likely driven by the serum IL-6 levels in COVID-19 patients." (PMID 36759861, 2023).